MIB1 (MIB E3 ubiquitin protein ligase 1)
Diseases named in the same sentence as MIB1 in open-access papers (continued):
Sharing a sentence is not in itself a finding about the gene and the disease.
tumor (continued). "It is strongly detected in low-grade tumours (well-differentiated) with low (MIB1) growth fraction, but is independent of the tumour progression (size, node status, CD31, and cathepsin D)." (PMID 9252201, 1997). "Finally, the remaining nine mice tumor specimens were processed for histological examination via standard hematoxylin and eosin (HE) staining and also examined for EMA, vimentin, and Ki‐67 (as detected by MIB‐1 antibody) via immunohistochemical (IHC) staining." (PMID 39996452, 2025). "Immunohistochemistry showed that tumor cells were S100+, CD34+, SOX10+, c-kit−, desmin−, DOG1−, ER−, HMB45−, STAT6−, Oct4−, synaptophysin−, AE1/AE3−, SMA−, and vimentin+; for a small fraction of cells, EMA+, synaptophysin−, BCL2−, and β-catenin− and MIB-1 positivity was about 1%." (PMID 40777560, 2025). "MIB1 assessment is usually performed via microscopic analysis of positive nuclei using manual counting and reporting as the percentage of positive nuclei per 1000 cells or 10,000 cells subjectively observed in tumor cells, but not in endothelial cells." (PMID 41614857, 2025). "In addition, S-phase kinase-associated protein 2 (Skp2) specifically degrades cyclin-dependent kinase inhibitor 1B (CDKN1B), and mindbomb homolog 1 (MIB1) enhances the ubiquitin-mediated degradation of suppression of tumorigenicity 7 (ST7); both Skp2 and MIB1 promote tumor proliferation." (PMID 38174069, 2023). "After complete tumor resection, ROI-based radio-pathological correlation analyses of the post-therapeutic specimen revealed increased values on the Ktrans-map in vital tumor parts, characterized by cells positive for MIB1- and ALDH1A1, compared to necrotic tumor parts." (PMID 37910565, 2023). "Nevertheless, we could not identify differences regarding the tumor size and myelomalacia signs in T2-weighted MR scans among the low or high MIB-1 labeling indices groups." (PMID 36091152, 2022). "GFAP staining was very low in the original tumor tissue, and absent in the 3D cultures and whereas MIB-1 signal strength was low, similar to that observed in the tumor tissue indicating that the spheroids recapitulated the mixed cell lineage and marker expression seen in the tumor." (PMID 35370679, 2022). "Additionally, cell proliferation indices were assessed using the MIB-1 antibody and demonstrated significantly higher proliferation indices for fluorescence-positive areas of tumor compared with negative areas." (PMID 30594965, 2019). "Also, due to the long period of data collecting starting in 1990, radiological data, especially MRI, tumor size and molecular biomarkers such as Mib-1 or Ki67 were not available for all patients and were included in the statistical analysis." (PMID 30976047, 2019). "Similarly, both cycling and non-cycling tumor cells (i.e. MIB-1 negative) were identified in the models as in the patient tumor." (PMID 28881750, 2017). "MIB-1 was also found to be positive in more than 50% of ER negative tumours." (PMID 24586570, 2014). "Additionally, MIB-1 LI was significantly higher in focally PpIX positive versus negative areas within the same tumor (mean MIB-1 LI: 15.9 versus 8.8%; p<0.0001)." (PMID 24204718, 2013). "The MIB-1 index was determined as the proportion of MIB-1-positive and MIB-1-negative tumour cells." (PMID 8855967, 1996).
tumor (continued). "Although we could not apply the MIB-1 labeling index of the tumor in multivariate analysis, univariate analysis indicated that a high MIB-1 labeling index, defined as more than 15%, might be a possible candidate for a prognostic factor for early recurrence (P = 0.020)." (PMID 24820480, 2014). "Immunohistochemical staining revealed that the tumor cells were positive for S100 protein, H3K27me3, and SOX-10 but negative for CD34 and MIB-1 index of 5%, indicating no malignancy." (PMID 40861330, 2025). "A significant correlation between MIB1-PR and SPF was found in aneuploid (P = 0.025) but not in diploid tumours (P = 0.164)." (PMID 9166949, 1997).
cancer (45 papers, 1999 to 2025). A tumor composed of atypical neoplastic, often pleomorphic cells that invade other tissues. "Various MIB1 mutations including missense, nonsense, silent mutations and frameshift deletions and insertions are observed in different cancers." (PMID 37746636, 2023). "The results from MIB1 immunostaining indicated that cancer cell proliferation was significantly suppressed in the 10% LA diet group: 64 ± 5/high-power fields of view (HPF) in control mice vs. 4 ± 0.3/HPF in 10% LA-treated mice (p < 0.001)." (PMID 35008652, 2021). "We provided a proof-of-concept prediction of the Ki67/MIB1 IHC positivity of cancer cells through the definition and quantitation of single nuclear features." (PMID 32466184, 2020). "In the present study, overexpression of JAM-A was found at the protein and mRNA levels in HNSCC tissues, where most cancer cells were positive for MIB1 as a proliferation marker." (PMID 27036044, 2016). "JAM-A was predominantly expressed on the membranes of cancer cells in which β-catenin and MIB1 were highly expressed." (PMID 27036044, 2016). "A similar lack of significant correlations occurred in comparing LA and AA levels in these tissues to cancer tissue levels of the 3 metabolites in patients with Mib1>20 scores." (PMID 23658799, 2013). "PGE2 and D2 trended lower in the cancer tissue of patients with Mib1>20 scores, grade II & III disease, high mitosis rate, and node metastasis." (PMID 23658799, 2013). "Ki-67, a gene expressed during G1, S and G2 phases of the cell cycle, with a peak during mitosis an absence in the G0 phase, is often measured using MIB-1 antibody as a labeling index for evaluating the proliferation status of numerous types of cancer." (PMID 23946777, 2013). "The growth rate of cancer is commonly estimated by measuring a cell proliferation-related protein, Ki-67, with Mib1 monoclonal antibody." (PMID 23658799, 2013). "Our results confirm these data, showing that in cortical adenomas, independently of their function, MIB-1 expression is similar to that in normal cortex, while in malignant tumours MIB-1 positivity appears to be strongly and constantly present." (PMID 12085205, 2002). "MIB-1 was expressed in all carcinomas with values (13.7±3.1%) significantly (P<0.0006) higher than in the other groups." (PMID 12085205, 2002). "Proliferative activity was expressed as the number of MIB1-positive nuclei per 1000 cancer cells in the most active areas of intraductal components (MLI-DCIS) or invasive foci (MLI-INV)." (PMID 10408711, 1999). "The MIB1 proliferation index ranged from 3–79% of cancer cell nuclei (median 31)." (PMID 36900270, 2023). "MIB1 silencing significantly inhibited cancer cell proliferation." (PMID 33793053, 2021). "Additionally, transwell assays revealed that MIB1 knockdown markedly impaired the invasion ability of cancer cells." (PMID 33793053, 2021). "Since MIB1 is an E3 ligase, we hypothesized that it promotes cancer development and progression by targeting tumor suppressor proteins for degradation." (PMID 33793053, 2021). "Ki-67 antigen is very sensitive to fixation and prolonged storage, which could explain failure of detecting elevated Ki-67/MIB-1 expression levels in some malignant tumors." (PMID 34181326, 2021). "There was no definite infiltration of the capsule and MIB1 count was low at 1 % thus the specimen lacked the diagnostic features of carcinoma." (PMID 27756436, 2016). "There was no perineural or vascular invasion and MIB1 count was low at 1 %; thus, the specimen lacked the diagnostic features of carcinoma." (PMID 27756436, 2016).
cancer (continued). "MIB-1 LI has been widely used as a cell proliferation marker in a variety of cancers." (PMID 24265731, 2013). "We then related their levels to each cancer’s proliferation rate as defined by its Mib1 score." (PMID 23658799, 2013). "The percentage of cancer cells with nuclear MIB-1 expression, ranged from 0 to 90% (median 10%)." (PMID 22333601, 2012). "MIB-1-LI results were all below 8% for G1 and above 30% for G3 carcinomas." (PMID 22662150, 2012). "Generally speaking, Ki67 (also known as MKI67, MIB-1, PPP1R105) is a very important biomarker for the proliferation index of cancers." (PMID 38370368, 2024). "SC can inhibit cell proliferation and induce cell apoptosis by decreasing MIB1‐mediated death associated protain kinase 1 (DAPK1) degradation, as well as enhance the chemosensitivity of TMZ to GBM, suggesting that SC might be a promising anti‐cancer agent for cancer therapy." (PMID 37346933, 2023). "Higher expression of JAM-A was found in the HNSCC region than in the adjacent dysplastic region, whereas in the differentiation-induced cancer pearl regions of HNSCC, the level of JAM-A was low as were those of β-catenin and MIB1." (PMID 27036044, 2016). "Moreover, Mindbomb E3 Ubiquitin Protein Ligase 1 (MIB1), an E3 ubiquitin ligase, was able to stimulate NRF2 degradation in a NOTCH-independent manner, rendering cancer more responsive to ferroptosis inducers." (PMID 40563292, 2025). "Tissue levels of ω6 FA, ω3 FA, total Sat FA, oleate, and ω3/ω6 ratios in the 4 tissues also failed to correlated significantly with cancer tissue levels of the 3 metabolites in all patients or patients with >20 Mib1 scores (results not shown)." (PMID 23658799, 2013). "The Ki67/Mib-1 proliferation index, however, does not allow an unequivocal discrimination between cancers with different "biological" behaviour." (PMID 16740156, 2006). "In fact, test results for cytokines AE1 and AE2 were negative (excluding the diagnosis of carcinoma), vimentin and smooth muscle actin were positive (confirming the sarcomatous nature of the lesion), and the proliferation index ‘MIB1’ was quantified to 60 percent." (PMID 23176176, 2012).
infection (5 papers, 2012 to 2024). The state of being infected such as from the introduction of a foreign agent such as serum, vaccine, antigenic substance or organism. "Sendai virus-induced IRF3 and TBK1 phosphorylation were dramatically reduced in MIB1/MIB2 double deficient MEFs compared to control mib1f/f MEFs in early infection." (PMID 23028469, 2012). "The E3 ubiquitin ligase Mib1 and proteasome promote infection by releasing the linchpin protein V from incoming adenovirus." (PMID 34919430, 2021). "In contrast, normal protein V is ubiquitinated at the nuclear pore complex, dissociates from the virion depending on the E3 ubiquitin ligase Mib1 and the proteasome, and allows genome delivery into the nucleus for infection." (PMID 34919430, 2021). "The reverted AdV-C5-V-KRrev* was strongly dependent on Mib1, similar to AdV-C5, indicating that K178/188 ubiquitination required Mib1 and was crucial for infection." (PMID 34919430, 2021). "To test whether ubiquitination of K178 and K188 was sufficient to restore the infection dependence on Mib1, we used AdV-C5-V-KRrev* to infect Mib1-KO cells." (PMID 34919430, 2021). "Mib1-KO cells are resistant to AdV-C5 infection but are susceptible to AdV lacking protein V or bearing non-ubiquitinable protein V, although the latter are less infectious than wild-type virus." (PMID 34919430, 2021). "To investigate how oHSV promotes NETosis, we found that oHSV infection increased IGF2BP3 and MIB1 expression while suppressing FTO in a time-dependent manner, along with the detection of viral proteins ICP0, ICP8, and gC." (PMID 38167409, 2024). "Our data here uncover that a virion linchpin protein V suppresses PAMPs and is inactivated by Mib1 and the UPS at the NPC, thereby triggering vDNA uncoating, nuclear import, and infection." (PMID 34919430, 2021). "Mib1-KO cells allowed full infection with AdV particles lacking protein V, which emphasizes the importance of Mib1-dependent ubiquitination of protein V in releasing viral genomes from stabilized capsids and nuclear import." (PMID 34919430, 2021). "Notably, infection of Mib1-KO cells with AdV-C5-∆V but not AdV-C5-∆IX was readily possible, while wild-type infection was blocked." (PMID 34919430, 2021). "Of the genes participating in metal ion binding (MIB1, KAT6B, ITGA8, HBAC, KCNC1, and F13A), most were downregulated during the later stages of GCRV infection, whereas genes involved in protein ubiquitination (HERC1 and HERC4) were upregulated during the later stages of infection." (PMID 28906455, 2017). "We tested whether the absence of protein V affected the infection of Mib1 knockout (KO) cells." (PMID 34919430, 2021).
adenocarcinoma (2 papers, 2007 to 2025). A common cancer characterized by the presence of malignant glandular cells.
benign neoplasm (2 papers, 2009 to 2014). A neoplasm which is characterized by the absence of morphologic features associated with malignancy (severe cytologic atypia, tumor cell necrosis, and high mitotic rate). "Assessing the proliferative index seems to be important, because all of the analyzed benign tumors showed <1% of MIB-1-positive cells." (PMID 19889235, 2009).
neurodevelopmental disorder (1 paper, 2024). A behavioral and cognitive disorder with onset during the developmental period that involves impaired or aberrant development of intellectual, motor, or social functions. "With respect to disease pathogenesis, the observed perturbations in her gene expression in the mib1 ta52 b mutants provide insights into potential mechanisms underlying both early developmental abnormalities and neurodevelopmental disorders associated with Notch signaling dysregulation." (PMID 39273123, 2024).
MIB1 also shares sentences with these, for which no sentence is quoted: Left ventricular noncompaction cardiomyopathy (3 papers); oligodendroglial tumor (2); adenosarcoma (1); adrenal carcinoma (1); aneurysm (1); Arrhythmia (1); asthma (1); atherosclerosis (1); atopic dermatitis (1); Atypical Meningioma (1); autoimmune disease (1); B-cell lymphoma (1); basal cell carcinoma (1); benign glioma (1); bladder cancer (1); bladder tumors (1); brain neoplasms (1); Cachexia (1); calcinosis (1); carcinomas of the adrenal cortex (1); cavernous angioma (1); cholesteatoma (1); chronic graft versus host disease (1); CNS tumors (1); colorectal adenocarcinoma (1); colorectal neoplasm (1); embryonal carcinoma (1); endometrial cancer (1); endometrial stromal sarcomas (1); endometrial stromal tumor (1).
A further 39 diseases each share a sentence with MIB1 in 1 paper.